MET (MET proto-oncogene, receptor tyrosine kinase)
Diseases named in the same sentence as MET in open-access papers (continued):
Sharing a sentence is not in itself a finding about the gene and the disease.
tumor (continued). "In mouse models, drugs, such as the oral multikinase inhibitor foretinib (with the dual inhibition of angiogenesis and c-MET signaling), proved to successfully deactivate the VEGFR2/MET signaling pathways and induce tumor cells' apoptosis." (PMID 31781608, 2019). "In proto-oncogenic proteins erbB-2, MET and FGFR, the enhanced and gain-of-carcinogenic effects by multimerization are also observed in tumor growth and cancer progression." (PMID 31439836, 2019). "To further evaluate the two-drug combinational approach in PDC models, we first determined the tumor cellular index in 5 HER2-positive and 3 MET-positive PDCs." (PMID 31850215, 2019). "HGF, MET-amplification, and EGFR-T790M upregulate PD-L1 expression in NSCLC and promote the immune escape of tumor cells through different mechanisms." (PMID 31747941, 2019). "The downregulated MCOLN3 and SLC25A45 with HR < 1 were considered as tumor suppressors, whereas the upregulated COL17A1, CEP55, KLK10, MET, ITGB6, ANKRD22, and ARNTL2 with HR > 1 were regarded as oncogenes." (PMID 31612115, 2019). "There was a clear trend of increasing gene expression levels of MET, MELK, SDC1 and TOP2A in primary tumor compared to normal samples." (PMID 31412643, 2019). "The recurrent tumour showed a 70–80 fold increase of expression of transcription factors ASCL1 and HOXA1 and tyrosine kinases FGFR3, HER3, HER4 and MET." (PMID 31747973, 2019). "MET activation further stimulates HGF production by CAFs, thus establishing a dynamic bidirectional ‘tumor-host signaling program’." (PMID 30544501, 2018). "Among three analyzed tumor-related genes, CTNNB1 and MET act as the oncogenes in HCC, and CCND1 is the hallmarker of cell cycle procession." (PMID 30327605, 2018). "miR-206 expression is very low in NSCLC and functions as a tumor suppressor through its downregulation of BCL2 and MET (hepatocyte growth factor receptor)." (PMID 29361709, 2018). "Recent data has demonstrated that RTKs, such as MET, EGFR, and PDGFR, regulate microRNA-134 in GBM, while microRNA-134 acts as a tumor-suppressive hub and controls KRAS and STAT5B expression levels." (PMID 29455648, 2018). "Note that one-time injection of MetMab at 5 mg/kg inhibited JHH5 tumor growth at the same level as INC280 daily oral dosing for 3 weeks, suggesting that neutralizing antibodies are a better choice than MET-TKIs in inhibiting HGF-autocrine tumors." (PMID 30208970, 2018). "For instance, c-MET appears to be important for the growth and maintenance of stem-like GBM cells, a population of tumor cells within glial brain tumors that is responsible for therapeutic resistance and progression." (PMID 29743557, 2018). "Here, we examined ALK, MET and mTOR as potential therapeutic targets and determined the combinatorial efficacy of ALK and mTOR targeting on tumor cell growth in vivo." (PMID 29755689, 2018). "Only in the cell lining of tumor VM vessels both NRP1 and MET were directly accessible from the vessel lumen (6A’)." (PMID 29854288, 2018). "As one possibility, Cui and co-workers demonstrated that the Forkhead box M1 (FOXM1) transcription factor regulates c-MET expression via ERK, AKT and STAT3 pathways, creating a positive feedback loop that promotes tumor growth." (PMID 30567565, 2018). "Upregulation of the c-MET pathway occurs as a consequence of the VEGFR inhibition, leading to tumor resistance to antiangiogenic medications and escape from VEGFR inhibition." (PMID 29892268, 2018). "Tepotinib MSC2156119J, highly selective ATP-competitive c-MET inhibitor, has been reported to suppress c-MET-positive HCC tumor in vivo." (PMID 30360560, 2018). "Matriptase plays important roles in both initiating tumor developments by triggering HGF/MET and PAR-2 or PI3K-Akt-mTor mediated signaling as well as tumor progression, including invasiveness and metastasis." (PMID 29899836, 2018).
tumor (continued). "NZ001, a novel dual inhibitor of MET and VEGFR2, markedly inhibited both tumor growth and metastasis of HCC, which showed obvious advantages over sorafenib in not inducing more invasive and metastatic behaviors." (PMID 29712569, 2018). "MET and VEGFR2 dual blockade, NZ001, resulted more pronounced inhibition on tumor growth and metastasis of HCC and showed advantages over sorafenib, especially not inducing more invasive and metastatic behaviors." (PMID 29712569, 2018). "Synthetically, these results provide strong evidence to show the inhibition role of miR-137 and miR-34a in tumor cell migration and invasion in CRC through regulation of c-MET." (PMID 30360560, 2018). "One of crucial mechanisms is that hypoxia increases MET expression in tumor cells through HIF-1α binding to the MET promoter and induces transcriptional activation of MET, which drives cell motility and invasion." (PMID 29712569, 2018). "Using a phospho-RTK array, we found that c-MET acts upstream of Akt, indicating that LAMB3 leads to tumor invasion via Akt activation induced by the HGF/c-MET axis in PTCs." (PMID 29426928, 2018). "When aberrantly activated, MET and its stroma-secreted ligand HGF (Hepatocyte Growth Factor) concur to tumor onset, progression, and metastasis in solid tumors, thus representing a relevant target for cancer precision medicine." (PMID 30544501, 2018). "We noted that the inhibition of IGF1R, MET, and AKT had a greater anti-tumor effect when combined with GDC0032 in both IGROV1Res and OAW42Res." (PMID 30237504, 2018). "Since MET and IGF1R expression limited the efficacy of GDC0032, we investigated the effect of these receptors on tumor cell viability in the presence of GDC0032 by conducting a head-to-head synergistic drug combination." (PMID 30237504, 2018). "We retrospectively analyzed the expression of matriptase, phosphorylated-MET (phospho-MET) and HAI-1 in tumor specimens obtained from patients with invasive bladder cancer by immunohistochemistry." (PMID 30469509, 2018). "Overall, MET and HGF concur to increase neovascularization, tumor expansion, and the release of neoplastic emboli into the bloodstream, regardless of the state of MET activation in cancer cells." (PMID 30544501, 2018). "PF-2341066, a small molecule inhibitor of c-MET and ALK, has been administered in ALCL with inhibition of tumor progression and apoptosis, as well as other c-MET inhibitors (e.g., SU11274 and PHA665752)." (PMID 29854308, 2018). "A recent study demonstrated that combinatorial treatment of a c-Met and ERBB inhibitor (capmatinib and afatinib) abolished tumor growth in NSCLC brain metastasis mouse models with MET amplification conferring acquired resistance to osimertinib." (PMID 29973561, 2018). "An online database of Gene Expression across Normal and Tumor tissues (GENT) containing more than 21,000 samples was used to confirm the higher expression of MET gene in tumor tissues, especially in GC tissues." (PMID 30158543, 2018). "HIF-1α can also regulate the c-MET/HGF pathway, which can induce tumor angiogenesis through stimulation of endothelial cell (EC) proliferation, migration, and tubulogenesis." (PMID 29560266, 2018). "When rapid tumor growth depletes local blood supply, long-term adaptation to hypoxia occurs through angiogenesis promoted by the HGF/MET axis." (PMID 30208970, 2018). "For example, MET is a proto-oncogene, KRAS is a proto-oncogene, and overexpression of RHOA leads to tumor formation." (PMID 29293623, 2018). "The CD44v6 peptide was more efficient than the c-MET inhibitor crizotinib and/or the VEGFR-2 inhibitor pazopanib in reducing xenograft tumor growth and metastasis." (PMID 29747682, 2018). "Studies have shown that tumor exosomes are involved in communication between tumor and normal cells, and help promote tumor growth and invasion through MAPK/ERK signaling and miR-338/MACC1/MET pathways, leading to changes that assist tumor progression." (PMID 30261592, 2018).
tumor (continued). "Previous studies with PHA665752 demonstrated that MET TKI alone or in combination with ionizing radiation induced DNA DSBs and apoptosis in tumor cells." (PMID 30208970, 2018). "Moreover, the c-MET amplification locus could be detected in circulating tumor DNA, suggesting that the early initiation of c-MET inhibitors in those patients who respond to anti-EGFR therapies and do not display emergence of KRAS mutations in blood tests during anti-EGFR therapies." (PMID 28368335, 2017). "Fibroblasts are the predominant constituent of the tumor stroma and Hepatocyte Growth Factor (HGF), the specific ligand for the tyrosine kinase receptor c-MET, is a major component of their secretome." (PMID 28420162, 2017). "Because HGF is frequently overexpressed in the tumor microenvironment, our work highlights the need to include inhibitors of biological activity of HGF into therapeutic regimen in MET-amplified NSCLC patients." (PMID 28968967, 2017). "Cabozantinib is an orally bioavailable TKI which targets VEGF receptors (VEGFRs), MET, AXL, and other receptor tyrosine kinases involved in tumor development and progression through angiogenesis, anti-apoptosis, invasiveness, metastasis, and drug resistance." (PMID 28247252, 2017). "In vitro, membrane c-MET was upregulated in HCC827ErlRes tumours by 213 ± 44% in relation to the level in HCC827 tumours, while c-MET was downregulated by 69 ± 9% in HCC827 tumours following treatment with NVP-AUY-922." (PMID 28315949, 2017). "In qualitative terms, Met3 and Met5 had comparable results of PC-3 tumors (human prostate cancer with high expression of c-MET) and SK-LMS-1/HGF tumors in mice models with high tumor/whole body ratio." (PMID 28485003, 2017). "Levels of total and phosphorylated EGFR, c-Met and ERK1/2 protein in tumor lysates were measured as indicators of receptor down-modulation (total EGFR and c-MET protein) and signaling pathway inhibition (phosphorylated protein)." (PMID 27786612, 2017). "In the dose-expansion cohort, a mean of 49.4% of cells had more than four gene copies of MET and a MET:CEP7 (centromeric region of chromosome 7) ratio ≥ 2, indicating tumor MET amplification." (PMID 29108334, 2017). "The patient’s tumor was tested for the alternative drivers ROS1 and MET that are known to be responsive to some ALK inhibitors but the results were negative." (PMID 28763012, 2017). "Due to its role in tumor progression and therapeutic resistance, both HGF and MET have emerged as valid therapeutic targets." (PMID 28420162, 2017). "MET, the receptor for HGF, can be activated to promote migration and invasion of tumor cells and provides a potential target for treating HCC." (PMID 28903454, 2017). "To this end, we employed a mass spectrometry-based custom-designed PCR assay for routine analysis of whole MET exon 14 and flanking intronic regions using formalin-fixed paraffin-embedded (FFPE) tumor samples." (PMID 28418914, 2017). "This study also suggested that the CD44v6 peptide was more efficient than the MET inhibitor crizotinib and the VEGFR-2 inhibitor pazopanib in reducing xenograft tumor metastasis." (PMID 28030817, 2017). "Among the 42 patients included in the study, 36 tumor re-biopsy samples were tested for MET FISH and 19 (52.8%) were found MET amplified." (PMID 29285237, 2017). "Based on our mutational data it is likely that the mutations that we detected in CBL were responsible for the enhanced expression of MET in HNSCC, since we determined high expression of Y1003 in our primary tumor specimens." (PMID 27244893, 2017). "Even though the loss of SOCS1 did not correlate with increased MET or p21 expression as we had expected, our findings support the tumor suppressor function of SOCS1, and the oncogenic potential of MET and p21 in PCa." (PMID 28235401, 2017). "First, presumably through the inhibition of c-MET/EGFR-dependent cell proliferation, overexpression of miR-206 inhibited tumor growth in SKOV3-inoculated nude mice." (PMID 29291022, 2017).
tumor (continued). "As a consequence of c-MET/EGFR inhibition, stable SKOV3 cells that expressed miR-206 displayed a retarded cell proliferation and tumor growth." (PMID 29291022, 2017). "MET tyrosine kinase plays an integral role in carcinogenesis by promoting tumor invasion, protection from apoptosis, and angiogenesis; binding to HGF or scatter factor activates MET." (PMID 28077782, 2017). "Despite mandatory submission of tumour samples for all participants, only 11, 16 and 18/31 patients had sufficient tissue for genotyping, AXL and MET expression respectively." (PMID 29050231, 2017). "Next, we tested cabozantinib (CB), a TKI that targets VEGF receptors (VEGFRs), MET, AXL, TIE-2, RET and other RTKs involved in tumor development and progression through angiogenesis, invasiveness, metastasis, anti-apoptosis and drug resistance." (PMID 29206199, 2017). "MET(cMet) is a member of the RTK family and plays a key role in tumor survival, growth, angiogenesis, and metastasis." (PMID 28292264, 2017). "We tested the antitumour effect of TAS-115 against Yamato-SS (c-MET-dependent SS cells) and SYO-1 (PDGFRα-dependent SS cells) xenograft tumours." (PMID 28511645, 2017). "Tumor cells that had adapted through therapy exhibited elevated HGF expression and the c-MET inhibitor crizotinib enhanced AR42 pazopanib lethality in this evolved drug-resistant population." (PMID 28146421, 2017). "In this cohort, Giannikopoulus and colleagues demonstrated the presence of SMO gene amplification in tumor biopsies taken at occurrence of resistance to EGFR-TKIs in 12,5% patients concomitantly with MET gene amplification." (PMID 28416737, 2017). "Activation of the HGF/c-MET pathway has been evaluated using serum or plasma HGF, because HGF is expelled from tumor cells to the extracellular matrix and blood plasma by a paracrine mechanism." (PMID 29069748, 2017). "Our key novel finding from in vitro and in vivo studies is that MET inhibition by SGX523 reduced proliferation and tumor growth in the H1975L858R/T790M cells and inhibited indices of stromal deposition in H1975L858R cells." (PMID 28141869, 2017). "To verify the inhibitory effects of TAS-115 and pazopanib on c-MET and PDGFRα in vivo, we administered TAS-115 (200 mg/kg) and pazopanib (100 mg/kg) orally to mice bearing Yamato-SS or SYO-1 xenograft tumours." (PMID 28511645, 2017). "For example, out of three cohorts of NSCLC patients with increasing MET/CEP7 ratios (1.8-2.2, 2.2–5.0 and above 5.0), the last had the highest tumor response rates to MET inhibitor crizotinib." (PMID 27924059, 2017). "Groups of three tumor samples studied by IHC were selected from the most RNA-overexpressed samples for EGFR, MET or CDK6, respectively." (PMID 27329726, 2016). "The results demonstrated that the ddPCR method has the potential to quantify the MET gene copy number with high precision and accuracy as compared with the results from SNP 6.0 and FISH in cancer cell lines and tumor samples, respectively." (PMID 26765781, 2016). "The prevalence of amplification of the MET gene was rare (less than 5%), and overexpression (more than IHC2+) of MET protein in tumor tissues were observed by IHC in 9–20% of advanced GC patients who previously underwent gastrectomy." (PMID 26716644, 2016). "In vivo experiments were performed to test the effects of c-MET inhibitor on tumor growth in orthotopic mouse xenografts of OCCC cell line RMG1 and a patient-derived tumor xenograft (PDX) model of OCCC." (PMID 27917934, 2016). "Tumor genotype was established using Sequenom Mass ARRAY; EGFR, PTEN, cMET and AXL expression was assessed by immunohistochemistry, circulating markers of EGFR activation (TGF-α, amphiregulin, epiregulin, EGFR ECD) by ELISA and EGFR, MET copy number by FISH." (PMID 27028852, 2016). "After SC injection these cells originated a tumor mass that recapitulated the heterogeneity of the primary tumor, including a subpopulation of RCC stem cells expressing CD105 and c-MET." (PMID 27322553, 2016).
tumor (continued). "MET‐pos‐NS were kept in a standard EGF/bFGF medium, supplied with HGF to better mimick the brain (tumor) microenvironment." (PMID 27138567, 2016). "In this study, we evaluated the heterogeneity of MET and EGFR expression in primary and metastatic TNBC tumorgrafts and evaluated the efficacy of MET and EGFR inhibition against tumor growth." (PMID 27655711, 2016). "The tumor cell lines evaluated in our study herein that harbor MET gene amplification, as defined by FISH analysis, and overexpress c-Met protein, are sensitive to ABT-700." (PMID 26879245, 2016). "Towards this goal we employed pharmacologic and genetic approaches to inhibit MET and identified the FDA approved drug crizotinib (PF-2341066), as a potent inhibitor of tumor progression and cellular proliferation of NF2-null Schwann cells." (PMID 27363027, 2016). "Tumor tissue and adjacent normal tissue samples were collected and subjected to cold ischemia prior to nanoproteomic analysis of AKT, ERK1/2, MEK1/2, and c-MET." (PMID 26742633, 2016). "We detected specific expression for EGFR, MET and CDK6 proteins in tumor cells of all tumor samples studied by IHC." (PMID 27329726, 2016). "Previously, reduced colony formation has been shown after inhibition of the type I IGF receptor with shRNA and the αIR3 antibody in MET-amplified MKN45 and in tumour explants, respectively." (PMID 27437872, 2016). "Here we report c-MET expression on CD105+ CD24− RCC stem cells which, implanted SC in NOD-SCID mice, recreate the heterogeneity of the primary tumor, including a subpopulation of RCC stem cells expressing CD105 and c-MET." (PMID 27322553, 2016). "A growing body of data points out that various miRNAs impede the growth of gefitinib-resistant tumours both in vitro and in vivo, meaning these effects can be attributed largely to the manipulation of EGFR/MET pathway and apoptotic cell death." (PMID 26891293, 2016). "In this study, we investigated the anti-tumor effect of TAS-115, a VEGFRs and HGF receptor (MET)-targeted kinase inhibitor, in a tumor-induced bone disease model." (PMID 27736957, 2016). "Many tumor types, including gastric, colorectal, renal, breast, pancreatic, lung, thyroid, and hepatocellular carcinoma, have aberrant activation of the HGF/MET signaling pathway." (PMID 27422720, 2016). "Binding of hepatocyte growth factor (HGF) to HGF receptor (c-MET) activates multiple key downstream signaling pathways such as the RAS/MAPK, PI3K/AKT and JAK/STAT, which play critical roles in tumor proliferation and survival." (PMID 27102149, 2016). "In conclusion, TAS-115 inhibited tumor growth via VEGFR-kinase blockade, and also suppressed bone destruction possibly through VEGFRs/MET/FMS-kinase inhibition, which resulted in potent efficacy of TAS-115 in an A549-Luc-BM1 bone disease model." (PMID 27736957, 2016). "On the basis of our findings, LECT2 is a potential therapeutic agent for HCC because it inhibits both tumor angiogenesis (anti-VEGFR2) and metastasis (anti-MET)." (PMID 27507763, 2016). "The tyrosine-kinase receptor c-Met (also known as MET) and its ligand, the hepatocyte growth factor (HGF), have been shown to be involved in tumour growth, invasion and metastasis in many human cancers of epithelial origin." (PMID 27896673, 2016). "Based on the drug potency achieved by adding FMS inhibition to VEGFRs/MET inhibition, and the good tolerability of TAS-115, we expect that TAS-115 will also exert prominent anti-tumor efficacy against bone metastasis in a clinical setting." (PMID 27736957, 2016). "Combination therapy dramatically reduced tumor growth, measured as GFP intensity, as compared with IR or MET inhibitor alone." (PMID 27138567, 2016). "Three additional groups of tumor samples were selected from normally expressed samples for both EGFR, MET and CDK6." (PMID 27329726, 2016).